MTFR2 (mitochondrial fission regulator 2)
Diseases named in the same sentence as MTFR2 in open-access papers (continued):
Sharing a sentence is not in itself a finding about the gene and the disease.
tumor (17 papers, 2019 to 2025). "Our findings revealed that the expression of MTFR2 was strongly associated with age (p=0.001), tumour grade (p=0.009), lymph node metastasis (p=0.010) and HER2 status (p=0.016)." (PMID 31740625, 2019). "Further evaluation of the relationship between MTFR2 staining and patient clinical characteristics showed that the MTFR2 protein level in BC tissues is associated with age, tumour grade, lymph node metastasis and HER2 status." (PMID 31740625, 2019). "Additionally, tumor tissues from mice injected with HCC alone or co‐injected with MTFR2‐deficient HSCs displayed fewer Ki67‐positive cells compared to those co‐injected with WT HSCs." (PMID 40365837, 2025). "However, recent studies have also shown that MTFR2 was associated with patient age, tumor TNM stage, molecular subtype, and grade, indicating poorer prognosis." (PMID 35600359, 2022). "In addition, univariate COX regression analysis showed neoplasm staging, T stage, distant metastasis and MTFR2 level were risk factors for the prognosis of LUAD." (PMID 34039308, 2021). "By linking our findings to the broader literature on mitochondrial dynamics and tumor metabolism, this study provides a foundation for exploring MTFR2‐targeted strategies in HCC management." (PMID 40365837, 2025). "Within the TME, HSC activation elevates MTFR2 expression, creating a stromal support system that sustains tumor growth through FA and mitochondrial provision." (PMID 40365837, 2025). "By integrating network pharmacology and weighted gene co-expression network analysis, critical gene modules linked to tumor phenotypes, EMT-related adverse prognosis, and elevated MTFR2 expression were identified, pinpointing the core target gene." (PMID 40748969, 2025). "Sorted cocultured Huh7 cells revealed that reduced MTFR2 expression in HSCs led to a significant decline in tumor cell proliferation, which was rescued by DRP1 overexpression." (PMID 40365837, 2025). "In vivo experiments confirmed that AS/BJO-NEs significantly inhibited tumor growth and reduced the expression of CDK1 and MTFR2 in tumor tissues." (PMID 40748969, 2025). "Exploring how MTFR2 modulates mitochondrial dynamics and influences cancer cell metabolism is critical to understanding its contribution to tumor biology." (PMID 40365837, 2025). "ROC analysis demonstrates that MTFR2 exhibits strong discriminatory power between tumor and non-tumor tissues in the TCGA-OSCC samples, with good predictive accuracy (AUC: 0.957)." (PMID 40748969, 2025). "NFYC promotes Akt signaling in HCC by activating MTFR2, which has a significant impact on tumor growth, metastasis, and metabolic reprogramming." (PMID 40165955, 2025). "We propose that this abnormal upregulation of MTFR2 is partly influenced by the posttranscriptional regulation mediated by the tumor suppressor miR-132-3p." (PMID 40129972, 2024). "Subgroup survival analyses revealed elevated MTFR2 expression correlated worse survival with clinical features including T3 stage, N0 stage, M0 stage, female, smoker, >65 years, residual R0 tumor, and pathologic stage." (PMID 35600359, 2022). "MTFR2 was abnormally expressed in pan-cancerous tissues, and was mainly over-expressed in a variety of tumor tissues." (PMID 34039308, 2021). "The results indicated that cells with down-regulated MTFR2 had a significantly reduced ability of inducing tumor formation compared with the controls." (PMID 33995638, 2021).
tumor (continued). "TIMER database was used to explore the correlation between MTFR2 expression level and immune cells infiltration and gene markers of tumor infiltrating immune cells." (PMID 33995638, 2021). "Next, we investigated the relevance between MTFR2 expression and the status of tumor-infiltrating immune cells based on the levels of immune marker genes in GC." (PMID 33995638, 2021). "In this study, we aimed to analyse the clinicopathological features of MTFR2 expression in BC patients and evaluate its biological functions in BC tumours." (PMID 31740625, 2019). "We compared 1085 BC tissues and 112 normal tissues from TCGA, and the results showed that MTFR2 expression was significantly higher in tumour tissues than in normal tissues (p<0.01)." (PMID 31740625, 2019). "Additionally, using the TCGA-PanCancer pan-cancer transcriptome data, we contrasted the differential MTFR2 expression between various tumor types and their corresponding normal control groups." (PMID 40748969, 2025). "In investigating whether MTFR2‐mediated tumor progression depends on DRP1, we performed sequential genetic manipulations: first suppressing MTFR2 via shRNA‐mediated knockdown, then restoring DRP1 expression through plasmid overexpression." (PMID 40365837, 2025). "Similarly, spheroid size analysis showed that DRP1 overexpression partially restored tumor growth that was impaired by MTFR2 knockdown." (PMID 40365837, 2025). "Similarly, expression of key mitochondrial proteins in Huh7 cells mirrored these changes, highlighting MTFR2‐driven mitochondrial transfer as a critical supporter of tumor metabolism and proliferation." (PMID 40365837, 2025). "Targeting MTFR2 to disrupt mitochondrial fission could impede the delivery of these vital metabolic resources, thereby curtailing tumor growth." (PMID 40365837, 2025). "In contrast, the AS/BJO-NEs may exert its anti-tumor effects by regulating CDK1 and down-regulating MTFR2, thereby inhibiting OSCC EMT and associated processes." (PMID 40748969, 2025). "However, tumor weight and volume were significantly greater in mice co‐injected with MHCC‐97H cells and WT HSCs compared to those with MHCC‐97H cells alone, while MTFR2 depletion impaired the ability of HSCs to enhance tumor growth." (PMID 40365837, 2025). "The findings suggest that targeting MTFR2‐driven mitochondrial fission may offer a novel therapeutic avenue for interfering with the metabolic crosstalk between tumor cells and the stromal niche." (PMID 40365837, 2025). "Moreover, AS/BJO-NEs can inhibit this series of processes by suppressing the expression of CDK1 and regulating MTFR2, thereby inhibiting the onset and progression of neoplasms, and modulating the tumor microenvironment and inflammatory environment." (PMID 40748969, 2025). "This study demonstrated that AS/BJO-NEs inhibited the proliferation, migration, invasion and EMT process of OSCC by down-regulating CDK1 and subsequently reducing MTFR2 expression, exerting anti-tumor effects and providing new possibilities and a theoretical foundation for OSCC treatment." (PMID 40748969, 2025). "This suggests a central role for MTFR2 in aHSC‐mediated tumor progression at the HCC margin." (PMID 40365837, 2025). "Secondly, MTFR2 has received significant attention due to its prominent role in regulating mitochondrial fission and is expressed at abnormal levels in multiple cancer tissues, facilitating tumor progression." (PMID 40748969, 2025). "Building on our prior observation that MTFR2 is overexpressed in aHSCs and promotes tumor cell proliferation via mitochondrial fission, we hypothesized that this effect is mediated through enhanced FAO." (PMID 40365837, 2025). "Additionally, the tumor weight in the MTFR2-si3 group was significantly lower than that in the control group." (PMID 40129972, 2024). "Moreover, the MTFR2-si3 group showed a significantly slower rate of tumor growth compared to the control group." (PMID 40129972, 2024).
tumor (continued). "Mitochondrial dynamics: The lncRNA MTFR2 (Mitochondrial Fission Regulator 2) has been shown in BC samples to increase invasion and tumor progression by modulation of metabolic orientation (glycolysis versus OXPHOS) by a Hypoxia Inducible Factor (HIF)-1alpha-dependent mechanism." (PMID 37958880, 2023). "In this study, we found that MTFR2 expression was significantly overexpressed in LUAD and a high expression of MTFR2 was associated with advanced TNM stages and poor survival in LUAD patients, which suggested that MTFR2 may be a tumor promoter in LUAD." (PMID 35600359, 2022). "However, currently available data on MTFR2 are insufficient in describing its role in tumor initiation and development." (PMID 33995638, 2021). "The results showed that MTFR2 was significant with tumor purity in GC (cor = 0.113, p =2.83E-02)." (PMID 33995638, 2021). "Secondly, the correlation analysis between MTFR2 and immune infiltration is performed under the condition of adjusting tumor purification, but the sequencing data may contain information from other cell sources, which requires tissue sample confirmation." (PMID 33995638, 2021). "MTFR2 was upregulated in 7 out of 8 tumors, while 1 tumor was undetectable." (PMID 32537437, 2020). "We next detected MTFR2 in 8 paired tumor and normal tissues." (PMID 32537437, 2020). "Our results demonstrate for the first time that MTFR2 is upregulated in BC tumours and that MTFR2 expression could predict poor survival." (PMID 31740625, 2019). "However, MTFR2 promoted mitochondrial division in cells, which was related to tumor progression." (PMID 34039308, 2021). "Moreover, subcutaneous tumors from MHCC‐97H cells co‐injected with MTFR2‐deficient HSCs exhibited lower levels of α‐SMA and COL1 compared to tumors co‐injected with WT HSCs, suggesting that MTFR2 deficiency in HSCs diminishes their capacity to promote tumor growth in vivo." (PMID 40365837, 2025). "Our findings establish MTFR2 in aHSCs as a key driver of HCC progression, orchestrating mitochondrial fission and the transfer of metabolic resources to tumor cells." (PMID 40365837, 2025). "We have verified that AS/BJO-NEs can play an anti-tumor role by down-regulating CDK1 and subsequently reducing the expression of MTFR2, as well as inhibiting the proliferation, migration and invasion capabilities of OSCC cells and the EMT process." (PMID 40748969, 2025). "In the Timer database, MTFR2 was highly expressed in BLCA, BRCA, CHOL, LUSC, LUAD and other tumor tissues." (PMID 34039308, 2021). "In particular, our data highlighted MTFR2, MND1, FAM72D, and POC1A as genes whose expression correlates with worse OS prognosis, suggesting their possible involvement in tumor progression and invasion." (PMID 31067633, 2019). "Mitochondrial fission regulator 2 (MTFR2), also called family with sequence similarity 54, member A (FAM54A), is poorly studied in tumours." (PMID 31740625, 2019). "Additionally, we investigated a series of tumor processes, especially EMT, triggered by the regulation of MTFR2 by this target." (PMID 40748969, 2025). "This MTFR2‐driven mitochondrial fission enhances the transfer of both fatty acids and mitochondria to HCC cells, supplying essential metabolic substrates and reinforcing the mitochondrial machinery critical for tumor growth." (PMID 40365837, 2025). "The results showed that MTFR2 exhibited high-level expression in tumor samples and displayed a significant negative correlation with the survival prediction of patients." (PMID 40748969, 2025). "Given that HSCs are lipid‐rich and fragmented mitochondria are smaller and more readily transferable, we propose that MTFR2‐mediated mitochondrial fission enables aHSCs to supply both FAs and functional mitochondria to adjacent HCC cells, fostering their interaction and supporting tumor growth." (PMID 40365837, 2025).
tumor (continued). "Moreover, our results showed a positive correlation between MTFR2 expression and Th2-cell infiltration levels, implying that MTFR2 overexpression in LUAD patients may trigger pro-tumor immune responses." (PMID 35600359, 2022).
cancer (14 papers, 2018 to 2025). A tumor composed of atypical neoplastic, often pleomorphic cells that invade other tissues. "Recent investigations have demonstrated increased expression of MTFR2 in cancer cells, which has been associated with unfavorable prognosis." (PMID 40129972, 2024). "Univariate Cox analysis of complete clinical data of LUAD patients in TCGA database showed that cancer stage, T stage, lymphatic metastasis as well as MTFR2 expression were risk factors for the prognosis of LUAD patients." (PMID 34039308, 2021). "Univariate Cox analysis showed that cancer stage, T stage, distant metastasis and the level of MTFR2 were risk factors for the prognosis in LUAD." (PMID 34039308, 2021). "Multiple lines of evidence have linked MTFR2 overexpression to cancer initiation and progression." (PMID 40129972, 2024). "Based on the results of these studies, MTFR2 is closely associated with cancer." (PMID 35600359, 2022). "Therefore, the GeneMANIA database was used to construct an interaction network between MTFR2 and other cancer-associated proteins." (PMID 33995638, 2021). "Mitochondrial fission regulator 2 (MTFR2) is known for its role in regulating mitochondrial fission and is expressed at abnormal levels in various cancer tissues, including CRC tissues." (PMID 38302953, 2024). "Our KEGG enrichment analysis revealed a significant correlation between elevated MTFR2 expression and microRNAs in cancer." (PMID 40129972, 2024). "In fact, a significant decrease in cancer cell proliferation, invasion, and migration was observed when MTFR2 was knocked down in HCT116 cells." (PMID 38302953, 2024). "For example, patients with HCC with mitochondrial fission regulator 2 (MTFR2) overexpression have poorer OS, which is associated with cancer stage, age, T stage, and grade." (PMID 37858067, 2023). "Based on the data extracted from TCGA-pan CANCER, TCGA-LUAD, and TCGA-GTEx-LUAD, we found that the MTFR2 expression levels were increased in TCGA pan-cancer and LUAD patients when compared to paired normal samples." (PMID 35600359, 2022). "Three databases (ONCOMINE, GEPIA2, and GENT) were mined to analyze MTFR2 expression levels among different cancers." (PMID 33995638, 2021). "Mitochondrial fission regulator 2 (MTFR2) was involved in the progression and development of various cancers." (PMID 34039308, 2021). "A series of experiments were applied and the results indicated that MTFR2 was upregulated in cancer tissue and negatively correlated with the overall survival (OS) of patients in both the TCGA database and our inhouse database." (PMID 32537437, 2020). "And MTFR2 promotes mitochondrial division and is involved in cancer development." (PMID 39871949, 2024). "The potential function of MTFR2 in normal cells or cancer cells has rarely been studied." (PMID 32537437, 2020). "MTFR2 is an oncogene involved in the progression of cancer, its' potential mechanism in oral squamous carcinoma remains unknown." (PMID 32537437, 2020). "Mitochondrial fission regulator 2 (MTFR2), ADP-ribosylation factor 1 (ARF1), and the ovarian tumor-associated protease deubiquitinase 6 A (OTUD6A) are also significantly overexpressed in CRC tissues, suggesting their potential roles in mitochondrial dynamics and cancer progression." (PMID 40750884, 2025). "Mitochondrial fission regulator 2 (MTFR2) belongs to the MTFR1 family, plays an important role in the regulation of oxidative phosphorylation and is also involved in cancer carcinogenesis and progression." (PMID 39871949, 2024).
cancer (continued). "Our study revealed a promising potential for CSC-target immunotherapy in the early stage of cancer and a probable value for PIMREG and MTFR2 as biomarkers and targets for immunotherapy." (PMID 33718103, 2020). "Mitochondrial fission regulator 2 (MTFR2), also termed as family with sequence similarity 54, member A (FAM54A), is a poorly investigated protein in human cancer." (PMID 29423030, 2018). "PIMREG and MTFR2 are considered as potential target genes in CSC population that are required for effective immune targeting, the pan-cancer analysis implies that these genes may also play important roles in other tumors." (PMID 33718103, 2020). "It was found that PIMREG, MTFR2, and CEP55 were overexpressed in BC and also in many other cancers." (PMID 33718103, 2020). "Subsequently, through pan-cancer transcriptome data, TCGA-OSCC transcriptome data, and clinical survival data, we conducted an analysis of the differential expression of MTFR2 across various tumors and the influence of high MTFR2 expression on the survival prognosis of OSCC patients." (PMID 40748969, 2025). "The relationship between MTFR2 and immune cells has not been explored in cancers." (PMID 35600359, 2022).
infection (1 paper, 2018). The state of being infected such as from the introduction of a foreign agent such as serum, vaccine, antigenic substance or organism. "In addition, among 46 TRP32 target genes previously found to be differentially expressed during infection, 8 are also TRP47 targets, including CAP1, CMC1, HLX, ING1, MTFR2, NAT10, PARP16, and POLDIP3." (PMID 30408047, 2018).
MTFR2 also shares sentences with these, for which no sentence is quoted: cervical cancer (1 paper); colon cancer (1); colorectal adenoma (1); ductal carcinomas (1); endometrial adenocarcinoma (1); glioblastoma (1); hematologic malignancies (1); leukemia (1); ovarian carcinoma (1); renal clear cell carcinoma (1); serous carcinoma (1).